SEMA5A (semaphorin 5A)
Description:
Bifunctional axonal guidance cue regulated by sulfated proteoglycans; attractive effects result from interactions with heparan sulfate proteoglycans (HSPGs), while the inhibitory effects depend on interactions with chondroitin sulfate proteoglycans (CSPGs) (By similarity). Ligand for receptor PLXNB3. In glioma cells, SEMA5A stimulation of PLXNB3 results in the disassembly of F-actin stress fibers, disruption of focal adhesions and cellular collapse as well as inhibition of cell migration and invasion through ARHGDIA-mediated inactivation of RAC1. May promote angiogenesis by increasing endothelial cell proliferation and migration and inhibiting apoptosis.
Synonyms: SEMAF; semF
Tractability: Small molecule: a structure with a bound ligand is known. Antibody: its Gene Ontology location is reachable by antibodies, with high confidence; UniProt predicts a signal peptide or a membrane-spanning region. PROTAC: ubiquitination databases record sites on it.
Gene: Protein-coding gene on chromosome 5 (9,035,033 to 9,546,142, reverse strand). Ensembl gene ENSG00000112902.
Subcellular location: Membrane
Pathways (Reactome):
Developmental Biology: Other semaphorin interactions
Disease: Defective B3GALTL causes PpS
Metabolism of proteins: O-glycosylation of TSR domain-containing proteins
Gene Ontology:
Molecular function: chemorepellent activity; chondroitin sulfate proteoglycan binding; heparan sulfate proteoglycan binding; semaphorin receptor binding; syndecan binding
Biological process: axon extension; axon guidance; axonal fasciculation; blood vessel endothelial cell proliferation involved in sprouting angiogenesis; cell adhesion; cell chemotaxis; cell-cell signaling; diencephalon development; negative regulation of axon extension involved in axon guidance; negative regulation of cell adhesion; negative regulation of endothelial cell apoptotic process; nervous system development; neural crest cell migration; positive chemotaxis; positive regulation of actin filament depolymerization; positive regulation of angiogenesis; positive regulation of axon extension involved in axon guidance; positive regulation of canonical Wnt signaling pathway; positive regulation of cell migration; positive regulation of endothelial cell chemotaxis; positive regulation of endothelial cell proliferation; positive regulation of phosphatidylinositol 3-kinase/protein kinase B signal transduction; semaphorin-plexin signaling pathway; signal clustering; negative chemotaxis
Cellular component: extracellular exosome; membrane; plasma membrane
Genetic constraint (gnomAD): Loss-of-function variants: 50 observed, 127.93 expected, observed/expected ratio (o/e) 0.39, 90% interval 0.31 to 0.5. The upper end of that interval is the gene's LOEUF score, 0.5, which puts it in group 2 of 6, group 1 being the genes least tolerant of losing a copy. Missense variants: 1,246 observed, 1,433.3 expected, observed/expected ratio (o/e) 0.87, 90% interval 0.83 to 0.91. Synonymous variants: 563 observed, 549.73 expected, observed/expected ratio (o/e) 1.02, 90% interval 0.95 to 1.1.
Homologues: Orthologues: chimpanzee SEMA5A (99% identical), macaque SEMA5A (98% identical), pig SEMA5A (94% identical), mouse Sema5a (94% identical), guinea pig SEMA5A (94% identical), rat Sema5a (94% identical), dog SEMA5A (91% identical), rabbit SEMA5A (85% identical), zebrafish sema5a (75% identical). Paralogues in human: SEMA5B (58% identical), SEMA6B (20% identical), SEMA6A (20% identical), SEMA6C (20% identical), SEMA6D (19% identical), SEMA4C (19% identical), SEMA3A (19% identical), SEMA4D (19% identical), SEMA3B (19% identical), SEMA3D (19% identical), SEMA3F (18% identical), SEMA3C (18% identical), and 7 more.
Diseases named in the same sentence as SEMA5A in open-access papers:
SEMA5A is named in the same sentence as 67 diseases in open-access papers, as found by Europe PMC text mining. Sharing a sentence is not in itself a finding about the gene and the disease. The quoted sentences say what the papers report.
glioma (22 papers, 2012 to 2025). A benign or malignant brain and spinal cord tumor that arises from glial cells (astrocytes, oligodendrocytes, ependymal cells). "This group also demonstrated that the SEMA5A/Plexin-B3 axis causes the astrocytic differentiation of glioma cells." (PMID 33669221, 2021). "Small nucleolar RNA host gene 18 (SNHG18) is significantly upregulated in clinical glioma tissues and is negatively associated with semaphorin 5A (Sema5A) expression." (PMID 31391206, 2019). "Fascin-1 and glial fibrillary acidic protein, GFAP, which is upregulated by sema5A, induce morphological changes in glioma cells and astrocytic differentiation of gliomas." (PMID 37627074, 2023). "SNHG18 inhibits Semaphorin 5A (SEMA5A) through competing endogenous RNAs (ceRNAs) to promote drug resistance in gliomas, and SNHG18 expression is related to tumor degree in gliomas." (PMID 36927398, 2023). "Another study reports that SNHG18 is overexpressed in glioma, and overexpression of SNHG18 reduces the radiosensitivity of glioma cells via inhibiting semaphorin 5A." (PMID 34937497, 2022). "Similar to our observation, Plexin-B3 and ligand SEMA5A were found to inhibit human glioma cell invasion." (PMID 33669221, 2021). "A recent study showed that inhibiting SNHG18 reduced the radioresistance of glioma cells via Sema5A." (PMID 31391206, 2019). "Several studies have demonstrated the expression and role of subclass-5 member Semaphorin-5A (SEMA5A) in various malignancies including glioma, lung, prostate, pancreas, melanoma and gastric." (PMID 29464045, 2018). "Li and Lee found that Sema5A inhibited the Rac1 GTPase through stimulation of plexin-B3, which resulted in the inhibition of glioma cell migration and invasion." (PMID 25780417, 2015). "The inactivation of Rac1 was confirmed to contribute to Sema5A-induced impediment of glioma cell migration and invasion, as evident by the abolishment of effect upon forced expression of a constitutively active Rac1 mutant." (PMID 23050142, 2012). "A recent report that investigates the significance of Sema5A and plexin-B3 in glioma has also shown their suppression of Rac1 activation, though through a different mechanism." (PMID 23050142, 2012). "Recently, Sema5A has been shown to suppress human glioma cell migration and invasion in a plexin-B3- and Rac1-dependent manner." (PMID 23050142, 2012). "Plexin-B3 was found to transduce inhibitory signals of sema5A in glioma cells." (PMID 37627074, 2023). "Furthermore, the protein product semaphorin 5A is reported to be up-regulated in glioma, melanoma, pancreatic, breast, and gastric cancer, and also is significantly elevated in rheumatoid arthritis." (PMID 33578652, 2021). "Upregulation of SNHG18 promotes resistance to radiotherapy in glioma by repressing Semaphorin 5A." (PMID 34950662, 2021). "SNHG18 promotes glioma resistance to radiotherapy by repressing semaphorin 5A." (PMID 34288803, 2021). "Indeed, Sema5A was found to reduce the motility of glioma cells, while having an opposite effect for the invasion of pancreatic, prostatic and gastric cancer cells." (PMID 30454024, 2018). "Up-regulation of snoRNA SNHG18 increases glioma cell radioresistance by repressing Semaphorin 5A." (PMID 30583549, 2018). "Interestingly, the semaphorin Sema5A has been shown to inhibit glioma cell motility, while this and other semaphorins seem to promote cancer growth and metastasis." (PMID 28698473, 2017). "SEMA5A inhibits glioma cell migration through RAC1 inactivation." (PMID 24516532, 2014). "Six out of the 17 interactions have been previously linked to invasion, migration or adhesion (EPHA4-Efnb3, SEMA5A-Plxnb3, AQP4-Dag1, FGFR1-Ncam1, FGF2-Sdc2, and APP-Aplp2) whereas only 3 interactions have been previously reported in glioma (SEMA5A-Plxnb3, AQP4-Dag1, and FGF2-Sdc2)." (PMID 25365423, 2014). "A downregulation of Sema5A protein is found from low- to high-grade gliomas." (PMID 23050142, 2012).
glioma (continued). "SEMA5A has not been associated with a univocal role in cancer, as it acts as a tumor promoter in cancers like gastric, prostate and, ovary while it acts as a tumor suppressor in glioma and lung cancer." (PMID 29464045, 2018). "Reduced expression of Sema5A was observed in clinical samples of high-grade astrocytomas compared to normal brain tissue, and Sema5A was found to inhibit migration and invasion in human glioma cells by interacting with the plexin-B3 receptor and disrupting Rac1 activity." (PMID 30454024, 2018). "This was the case for SEMA5A (FDR = 0.0855), DRD2 (FDR = 0.00623) and SOSTDC1 (FDR = 0.0234), which have all been found to act as tumor suppressors in pancreas cancer, glioma, non-small cell lung cancer and thyroid cancer." (PMID 34604945, 2021). "In comparison to the grade III sample, ECM-affiliated genes (COLEC12, SDC2 and SEMA5A) showed enhanced spatial expression in GBM regions with perivascular microgliosis associated with pseudopalisading necrosis, that are largely absent in lower-grade gliomas." (PMID 41366031, 2025). "In non-neuronal cells, Sema5A signals in a PlexB3-dependent manner to elicit distinct cytoskeletal responses, including collapse of NIH3T3 cells, motility of glioma cells, and migration of primary endothelial cells." (PMID 25313870, 2014).
autism (17 papers, 2011 to 2025). Persistent deficits in social interaction and communication and interaction as well as a markedly restricted repertoire of activity and interest as well as repetitive patterns of behavior. "The expression of one with no established function in the brain Sult6b1, one with association to Autism Sema5a, and one with well-established role in the brain Ccl7 was examined." (PMID 38721690, 2025). "All criteria for the recruitment model were fulfilled by one gene, Sema5a, which is an autism-susceptibility gene with a role in axon guidance and synaptogenesis." (PMID 36598943, 2023). "Semaphorin 5A gene has been linked to autism, and additionally, the failure of its expression has been linked to abnormal development of the axonal connections in the forebrain." (PMID 35501678, 2022). "Along with GWAS on autism, a few recent studies suggested the association of Sema5A and Sema3F with ASD." (PMID 32443632, 2020). "Deleting a gene called Sema5A, which has been linked to autism in humans, causes neurons to form more connections in mice, and also alters how these mutant mice interact with other mice." (PMID 25407769, 2014). "The gene that codes for a protein called SEMA5A has been identified as an autism susceptibility gene in humans." (PMID 25313870, 2014). "Alternatively, for example, knockin mice, harboring the R676C or S951C mutation of Sema5A, may actually reflect some types of autism in humans." (PMID 38133141, 2023). "Cumulative evidence obtained from various sources shows that SEMA5A is a transmembrane protein that has been identified as an autism susceptibility gene in humans according to a genome-wide association study, cDNA microarray technology and expression quantitative trait locus mapping." (PMID 31354784, 2019). "Human SEMAPHORIN 5A (SEMA5A) is an autism susceptibility gene; however, its function in brain development is unknown." (PMID 25313870, 2014). "Using cDNA microarray technology, some transcripts, including the sema5a gene, have been identified to be downregulated in autism patients." (PMID 38133141, 2023). "Genome-wide ASD association analyses have identified an intergenic SNP near the SEMA5A locus, and this same study showed that SEMA5A expression is reduced in Brodmann area 19 of autism brains." (PMID 25313870, 2014). "These nearest genes include candidate genes for which strong proximal associations with autism have previously been reported, such as CDH9 and SEMA5A." (PMID 21247446, 2011). "Thus, PlxnA2−/− mice exhibit symptoms of Schizophrenia, Sema3F−/− mice exhibit symptoms of anxiety and autism, and Sema5A−/− mice exhibit symptoms of autism." (PMID 38646100, 2024). "The structure and function of Sema5A may be altered by amino acid substitutions in autism, affecting neuronal cell morphogenesis and morphologies." (PMID 38666924, 2024). "The structure and function of Sema5A are modified by their amino acid replacements in autism." (PMID 38133141, 2023). "Further analyses using various types of Sema5A genetically modified mice will allow us to determine whether knockout or transgenic Sema5A mice reflect early or later onset autism, or both types." (PMID 38133141, 2023). "This phenomenon may result in the formation of sufficient networks between synapses in the later developmental periods, although it remains to be determined how much Sema5A knockout mice reflect early onset autism and the developmental abnormality in humans." (PMID 38133141, 2023). "SEMA5A (semaphorin 5A), another gene of the semaphorin family, was identified to be an ASD-associated gene, and there was evidence of decreased expression of this gene in patients with autism." (PMID 34922566, 2021). "Semaphorin 5A (SEMA5A) is known to be responsible for certain types of autism." (PMID 27171439, 2016).
autism (continued). "When coupled with the impaired social behavior we observe in Sema5A−/− mice, our studies begin to provide mechanistic insight into how altered SEMA5A function may lead to brain illness, including autism." (PMID 25313870, 2014). "Sema5A−/− mice exhibit impaired sociability, a core trait of ASD that has been observed in several mouse models of autism." (PMID 25313870, 2014).
autism spectrum disorder (13 papers, 2014 to 2025). A spectrum of developmental disorders that includes autism, and Asperger syndrome. "Specific polymorphisms in SEMA5A have been implicated in autism spectrum disorders and Parkinson’s disease." (PMID 33578652, 2021). "Potentially of interest, it has also been associated with autism spectrum disorders via a semaphorin 5A (SEMA5A) eQTL network." (PMID 33115496, 2020). "FOXP2 plays a role in neurogenesis and is involved in language and speech disorders SEMA5A, which encodes members of the semaphorin family, has been implicated in axonal guidance and is a candidate gene in autism spectrum disorder." (PMID 27483351, 2016). "A deletion in the SEMA5A gene has been associated with autism spectrum disorders." (PMID 39975073, 2025). "In addition, we identified a close protein-protein interaction network between SEMA5A and candidate genes associated with epilepsy, autism spectrum disorder (ASD) or intellectual disability." (PMID 31354784, 2019). "Previous studies have suggested that SEMA5A could be a susceptibility gene for autism spectrum disorders (ASDs)." (PMID 26395558, 2016). "Sema5A−/− mice display deficits in social interaction, a hallmark of autism-spectrum-disorders." (PMID 25313870, 2014). "Additionally, we observed ectodermal EtOH-induced alterations in several genes, such as LHX2, SHANK2, TRIO, ZMYND8, ARX, NRXN3 and SEMA5A, that have also been associated with autism spectrum disorder (ASD) (SFARI Gene Database, 2024; accessed: 1, August, 2024)." (PMID 40401629, 2025). "Importantly, mutations in the gene encoding Sema5A have been strongly associated with autism spectrum disorder (ASD) and, in some cases, with intellectual disability (ID), which is characterized by below-average cognitive performance along with deficits in conceptual and social communication." (PMID 41226692, 2025). "These experiments identify novel intra-dendritic Sema5A/PlexinA2 interactions that inhibit excitatory synapse formation in developmentally born and adult-born GCs, and they provide support for SEMA5A contributions to autism-spectrum-disorders." (PMID 25313870, 2014). "SEMA5A is a transmembrane protein that regulates the development of connections between neurons, but it is not known how mutations in the gene for SEMA5A might lead to brain illnesses such as autism spectrum disorders." (PMID 25313870, 2014).
pancreatic cancer (11 papers, 2015 to 2022). "A study demonstrated that the expression of SEMA5A, a member of the semaphorin V subfamily, is associated with tumor growth, invasion, and metastasis in pancreatic cancer cells." (PMID 29977159, 2018). "In vitro assays indicated that Sema5A is actively stimulating pancreatic cancer cell migration, via PlexinB3 receptor-associated Met tyrosine kinase; however gene knock-down experiments revealed that the role of Sema5A in PDAC is complex and needs further elucidation." (PMID 33537086, 2021). "Semaphorin 5A has been linked to tumor growth, invasion, and metastasis in pancreatic cancer." (PMID 29977159, 2018). "However, overexpression of Sema5A in pancreatic cancer has been shown to correlate with invasion, metastasis and increased endothelial cell proliferation, while overexpression of Sema5A and plexin-B3 are associated with the invasion and metastasis of gastric carcinoma." (PMID 25780417, 2015). "For example, SEMA5A was found to be upregulated in pancreatic cancer and was correlated with tumor growth, invasion, and metastasis." (PMID 35269749, 2022). "We saw the tumor-specific and metastasis-specific roles of Semaphorin-5A, a ligand of Plexin-B3, in pancreatic cancer." (PMID 33669221, 2021). "Our group has identified Semaphorin-5A (SEMA5A)/Plexin-B3 as an attractive targetable complex for pancreatic cancer (PC) metastasis." (PMID 33669221, 2021). "Previously our group identified Semaphorin-5A (SEMA5A), the ligand of Plexin-B3, involved in organ-specific homing of pancreatic cancer (PC) cells and plays a significant role in PC angiogenesis and metastasis." (PMID 33669221, 2021). "Using human patients and different mouse models, we demonstrated that SEMA5A expression was highest in liver metastases, followed by primary pancreatic tumors, and the lowest expression was found in the normal pancreas." (PMID 29464045, 2018). "We observed that progressive increase of of SEMA5A expression from pre-cancerous lesions (10-weeks of age) to pancreatic cancer (50 weeks of age)." (PMID 29464045, 2018). "Previous reports from our laboratory have identified one such molecule SEMA5A, which demonstrated differential expression in pancreatic tumors in comparison with the normal pancreas." (PMID 30577767, 2018). "Semaphorin-5A (SEMA5A) has differential cell surface expression between normal and cancer cells and represents an attractive target for therapeutic intervention in pancreatic cancer (PC)." (PMID 29464045, 2018). "In conclusion, SEMA5A signaling represents a potential molecule for targeting metastasis in pancreatic cancer." (PMID 29464045, 2018). "However, the secreted form of SEMA5A suppressed the proliferation of pancreatic cancer cells while also displaying tumor-promoting activities in gastric cancer." (PMID 35269749, 2022). "SEMA5A has also been shown to modulate motility and metastasis of gastric and pancreatic cancers." (PMID 35269749, 2022). "Thus, the SEMA5A axis represents a potential target for the diagnosis and treatment of pancreatic tumors in the future." (PMID 29464045, 2018). "We analyzed SEMA5A expression on differentiation status of the tumor and observed that SEMA5A expression was significantly higher (p < 0.05) in well differentiated and moderately differentiated tumors in comparison with poorly/undifferentiated tumors as well as normal pancreatic tumors." (PMID 29464045, 2018). "SPSB4 was identified among five genes, ADAMTS2, HOXA1, PCDH10, SEMA5A and SPSB4, that were highly/frequently methylated in liquid biopsies of pancreatic cancers although with a relatively low potential compared with the other four markers." (PMID 34062897, 2021). "Of the three criteria, we identified eight genes that were the most highly/frequently methylated in pancreatic cancers (PCDH10, SPSB4, HOXA1, ADAMTS2, BMP3, C13orf18, CCND2, and SEMA5A)." (PMID 32520974, 2020).